USP12 (ubiquitin specific peptidase 12)
Diseases named in the same sentence as USP12 in open-access papers (continued):
Sharing a sentence is not in itself a finding about the gene and the disease.
viral infection (3 papers, 2020 to 2023). "USP12 interacted with viral capsid protein (CP) in Epinephelus coioides to inhibit viral infection and positively regulated the levels of associated inflammatory factors, including TNF-α, IL-1β, IL-6, IL-8, IRF, and IRF7." (PMID 37752518, 2023). "Importantly, in STAT1-deficient cells (U3A), the ability of USP12 to inhibit viral infection was largely attenuated." (PMID 31899788, 2020). "Studies have illustrated that USP12 was associated with many aspects of TME, including immune checkpoints, chemokines, immune cells and viral infection." (PMID 37752518, 2023). "To characterize the role of USP12 in virus infection in vivo, we infected wild type (WT) and Usp12-/- mice with HSV-1 and VSV via tail vein injection and monitored their survival." (PMID 37410794, 2023). "To explore the potential role of USP12 in antiviral immunity, we first detected the expression of USP12 after virus infection and found that USP12 expression was induced by HSV-1 infection, which was mainly regulated by NF-κB p65 and IRF3, but not by STAT1." (PMID 37410794, 2023). "The replication of HSV-1 and VSV exacerbated 4 d after viral infection in the lungs, spleens and brains of Usp12-/- mice compared with that in the lungs and spleens of WT mice." (PMID 37410794, 2023). "As a consequence, both USP12-C48A and USP12-C48S significantly inhibited viral infection with a similar efficiency as USP12-WT." (PMID 31899788, 2020). "Consistently, as compared with USP12-WT, the USP12-C48S/H173D mutant had a similar ability to inhibit viral infection." (PMID 31899788, 2020). "Given that viral infection stimulates IFN secretion, we speculated that virus-induced IFN signaling could be enhanced by USP12." (PMID 31899788, 2020).
cardiac hypertrophy (2 papers, 2022 to 2023). "For example, USP12 overexpression could exacerbate Ang II-induced cardiac hypertrophy by raising the METTL3 level." (PMID 37752518, 2023). "According to a recent study, USP12 (ubiquitin-specific protease 12) via enhancing p300/MTLL3 axis promote myocardial hypertrophy, and our finding may indicate the possibility of m6A methylation and ubiquitination cooperatively regulate heart growth." (PMID 35858921, 2022). "USP12 inhibits the degradation of p300 by deubiquitinating its K48-linked polyubiquitination chains and stabilizes p300 protein, which in turn promotes METTL3 transcription via enhancing METTL3 promoter activity and eventually exacerbates Ang II-induced cardiac hypertrophy." (PMID 37752518, 2023).
cervical carcinoma (2 papers, 2015 to 2022). A carcinoma arising from either the exocervical squamous epithelium or the endocervical glandular epithelium. "It was confirmed through the TCGA database that the frequency of mutations and deep deletions of USP12 are high in cervical cancers." (PMID 36361894, 2022). "In addition, deep deletions and mutations of USP12 with high frequency were observed in cervical cancer cells through informatics analysis." (PMID 36361894, 2022). "Future studies of the anticancer activity of Bax and USP12 proteins are recommended in cervical cancer cell lines." (PMID 36361894, 2022). "Therefore, we conducted experiments on the interaction of USP12 with Bax in the cervical cancer cell line, HeLa." (PMID 36361894, 2022).
colorectal cancer (2 papers, 2023 to 2026). A primary or metastatic malignant neoplasm that affects the colon or rectum. "The overexpression of USP12 in human colorectal cancer cells was previously found to inhibit cell proliferation, and siUSP12 could reverse this effect." (PMID 37752518, 2023). "Also, USP12 negatively regulated the expression of PD-L1 on MDSCs in colorectal cancer." (PMID 37752518, 2023). "In this study, we examined PD-L1 expression in various types of immune cells in human colorectal cancer in connection to cancer progression-specific USPs, including USP10, USP12, USP14, USP18, USP32, USP33, and USP39." (PMID 41356798, 2026).
Fanconi anemia (2 papers, 2012). Fanconi anemia (FA) is a hereditary DNA repair disorder characterized by progressive pancytopenia with bone marrow failure, variable congenital malformations and predisposition to develop hematological or solid tumors. "Interestingly, UAF1/WDR48 can fully activate the DUB activity of USP1, which regulates the Fanconi anemia DNA repair pathway, but only weakly stimulates the catalytic activity of USP46 and USP12, whereas full activation of USP12 requires ternary complex formation with both UAF-1/WDR48 and WDR20." (PMID 23316392, 2012).
gastric cancer (2 papers, 2024 to 2025). A primary or metastatic malignant neoplasm involving the stomach. "USP12 was found to be upregulated in patients with gastric cancer and was associated with poor survival in gastric cancer." (PMID 38605077, 2024). "Furthermore, it was discovered that the elevated expression of USP12 was associated with poor survival specifically in gastric cancer patients." (PMID 38605077, 2024). "Besides, the KMplot database analysis revealed that USP12 is associated with poor survival in gastric cancer patients." (PMID 38605077, 2024). "The results indicate that high USP12 expression is linked to a poor prognosis in gastric cancer and may be a crucial oncogene of the disease." (PMID 38605077, 2024). "We conducted additional research on USP12 expression in human gastric cancer, revealing elevated levels of USP12 in gastric cancer according to data from the TCGA database (p < 0.001, FC = 1.18)." (PMID 38605077, 2024). "By the CCK8 assay, it was observed that the proliferation of gastric cancer cells was suppressed by USP12 deletion, and this inhibition was partially mitigated by YAP overexpression." (PMID 38605077, 2024). "The deubiquitinase siRNA library screen identified USP12 as a potential deubiquitinase involved in gastric cancer progression and the Hippo/YAP axis." (PMID 38605077, 2024). "In the currently study, we performed siRNA screening and identified that USP12 is essential for controlling the stability of the YAP protein in gastric cancer." (PMID 38605077, 2024). "In conclusion, we confirmed USP12 as an oncogene in both in vitro and in vivo models of gastric cancer." (PMID 38605077, 2024). "Our research uncovers a novel mechanism of post-translational regulation for Hippo signaling, identifying USP12 as a promising target for therapeutic intervention in gastric cancer." (PMID 38605077, 2024). "We conducted phenotypic rescue experiments to further investigate the impact of USP12 deletion on gastric cancer cells." (PMID 38605077, 2024). "This suggests that the promotion of gastric cancer progression by USP12 is dependent on its deubiquitinating enzyme function." (PMID 38605077, 2024). "Due to USP12 as an oncogene in gastric cancer, we further explored the biological function in gastric cancer cell lines." (PMID 38605077, 2024). "The in vivo and in vitro experiments demonstrated that USP12 is necessary for the growth of gastric cancer." (PMID 38605077, 2024). "We further investigated the potential mechanism of action of USP12 in regulating gastric cancer progression through the Hippo/YAP pathway." (PMID 38605077, 2024). "To achieve this, we categorized the transcriptome samples of gastric cancer samples in the TCGA database into two cohorts based on high and low USP12 expression levels (50% vs. 50%)." (PMID 38605077, 2024). "As a result, we have identified a novel regulatory mechanism involving USP12 and Hippo signaling in the progression of gastric cancer, with the potential for blockade of USP12 to materialize as a promising strategy for combating gastric cancer." (PMID 38605077, 2024). "Our bioinformatic analysis further demonstrated a correlation between USP12 and poor survival, as well as a positive association with classical YAP target genes in gastric cancer samples." (PMID 38605077, 2024). "Notably, USP12 depletion was found to inhibit gastric cancer progression via the Hippo/YAP axis, whereas USP12 overexpression exhibited the opposite effect, promoting gastric cancer growth and enhancing YAP activity." (PMID 38605077, 2024). "CCK8 assays showed that deletion of USP12 inhibited gastric cancer cell proliferation." (PMID 38605077, 2024). "Furthermore, bioinformatic analysis revealed a possible association between USP12 and the YAP signature gene cluster in gastric cancer." (PMID 38605077, 2024). "Our study showed that the expression of USP12 was increased in gastric cancer." (PMID 38605077, 2024).
gastric cancer (continued). "We further investigated the function of USP12 in Hippo/YAP signaling pathway in gastric cancer." (PMID 38605077, 2024). "Our research uncovered a new functional connection between USP12 and YAP, suggesting that USP12 could potentially be a valuable target for drug development in the management of gastric cancer." (PMID 38605077, 2024). "In conclusion, our findings suggest that USP12 plays an intriguing regulatory role in the modulation of Hippo signaling in gastric cancer, suggesting that USP12 could serve as a potential target for the Hippo/YAP axis in the context of gastric cancer." (PMID 38605077, 2024). "USP12 activation facilitates gastric cancer progression by modulating YAP stability." (PMID 38605077, 2024). "Besides, USP12 interacted with YAP protein, suppressing YAP poly-ubiquitination by K48-linked and preventing proteasome-mediated degradation in gastric cancer cells." (PMID 38605077, 2024). "Therefore, targeting USP12 activity or gene expression could provide an attractive strategy for treating gastric cancer." (PMID 38605077, 2024). "Furthermore, gastric cancer patients with high expression of USP12 exhibit a poor survival." (PMID 38605077, 2024). "To assess the catalytic activity of deubiquitinating enzymes in USP12 contributes to the phenotype of gastric cancer cells, we overexpressed USP12 wild-type (USP12WT) and USP12 enzyme-inactivated mutants (USP12C48S)." (PMID 38605077, 2024). "Subsequent biological studies confirmed the essential role of USP12 in the Hippo/YAP axis and the progression of gastric cancer." (PMID 38605077, 2024). "In an effort to shed light on effective therapeutic targets, we conducted a screening using a deubiquitinase small interfering RNA library, leading to the identification of USP12 as an important deubiquitinase in the context of Hippo/YAP axis and the progression of gastric cancer." (PMID 38605077, 2024).
amyotrophic lateral sclerosis (1 paper, 2018). Amyotrophic lateral sclerosis (ALS) is a neurodegenerative disease characterized by progressive muscular paralysis reflecting degeneration of motor neurons in the primary motor cortex, corticospinal tracts, brainstem and spinal cord. "Identification of Usp12 as a modifier of HD suggested that Usp12 could rescue neurodegeneration in related disorders, such as amyotrophic lateral sclerosis (ALS) and Parkinson’s disease (PD) that are characterized by proteotoxic stress." (PMID 30266909, 2018).
autoimmune disease (1 paper, 2021). A disorder resulting from loss of function or tissue destruction of an organ or multiple organs, arising from humoral or cellular immune responses of the individual to their own tissue constituents. "Although USP12-deficient CD4+ T cells protected mice from autoimmune diseases, the immune response against bacterial infection was subdued." (PMID 33941870, 2021). "Although USP12 deficiency protected mice from autoimmune diseases, it resulted in lower in vivo CD4+ T cell responses to L. monocytogenes infection." (PMID 33941870, 2021). "In the present study, we found that USP12 plays a vital role in the pathogenesis of autoimmune disease and bacterial infection." (PMID 33941870, 2021). "Our study highlighted the critical role of USP12 in regulating the adaptive immune responses that occur during autoimmune disease and infection." (PMID 33941870, 2021). "Although USP12 activated CD4+ T cell responses against bacterial infections, it also promoted autoimmune disease development." (PMID 33941870, 2021).
colon cancer (1 paper, 2026). "Interestingly, USP32 and USP12 have been repeatedly found at elevated levels in T-cells, macrophages, and classical monocytes associated with colon cancer compared with levels in the control group." (PMID 41356798, 2026). "USP32, USP1, USP37, USP12, and USP6 are elevated in macrophages, while USP32, USP9X, USP46, USP12, USP36, and USP24 are upregulated in classical monocytes of colon cancer relative to the control group." (PMID 41356798, 2026).
HCMV infection (1 paper, 2023). "As USP12 has been reported to antagonize PTPN2’s dephosphorylation of pSTAT1, it is also possible that interaction with USP12 contributes to UL138-mediated sustainment of pSTAT1 during HCMV infection." (PMID 37289831, 2023). "Sustainment of pSTAT1 by USP12 may be coordinated with that of USP1 in the context of HCMV infection or they may function distinctly under different contexts." (PMID 37289831, 2023). "We did not directly test the role of the UAF1 scaffold in HCMV infection, as its knockdown is likely to have pleiotropic effects due to the combined loss of USP1, USP12, and USP46 activity." (PMID 37289831, 2023).
immune deficiency (1 paper, 2014). "However, a previous report from our group identified the Drosophila ortholog of USP12 as a modifier of the immune deficiency (IMD) pathway." (PMID 25071782, 2014).
Lewis lung carcinoma (1 paper, 2021). "To corroborate these observations, we compared the tumour growth of Lewis lung carcinoma (LLC) cells with or without genetic manipulation of USP12 expression." (PMID 34381028, 2021).
lung adenoma (1 paper, 2021). A benign, well circumscribed epithelial neoplasm that arises from the bronchus or the lung parenchyma. "Given the abundant USP12 downregulation in NSCLC and mouse lung tumours, we next examined whether USP12 regulated tumour growth in the KrasG12D-driven lung adenoma model by lentivirally delivery of Cre recombinase alone or Cre together with USP12 (USP12;Cre)." (PMID 34381028, 2021). "The regulation of PPM1B by USP12 was recapitulated in mouse KrasG12D-driven lung adenomas and some of the human NSCLC tissues examined, as evidenced by low levels of PPM1B and USP12 concurrently presented in tumour cells." (PMID 34381028, 2021).
periodontitis (1 paper, 2025). An acute or chronic inflammatory process that affects the tissues that surround and support the teeth. "In conclusion, USP12 inhibition is a protective strategy for periodontitis treatment." (PMID 39626954, 2025).
tumor (16 papers, 2012 to 2025). "We found that decreased expression of USP12 was present in tumours with different driver gene mutations, suggesting that the downregulation of USP12 is not a phenomenon specifically linked to the KRAS mutant." (PMID 34381028, 2021). "Mechanistically, USP12 downregulation creates a tumour-promoting secretome resulting from insufficient PPM1B deubiquitination that causes NF-κB hyperactivation in tumour cells." (PMID 34381028, 2021). "Given the relevance of the USP12-mediated chemokine, such as CXCL8, CXCL1 and CCL2, in tumour development and progression, we examined the mechanism underlying the USP12-mediated regulation." (PMID 34381028, 2021). "And abnormalities also involve gene mutations in PTEN, SIRPA, TBK1, the Y chromosome, as well as immune cells and stromal cells such as Treg, MDSCs, TAMs, CAFs, loss of tumor immunogenicity, abnormalities in Indoleamine 2,3-dioxygenase, Ubiquitin-specific protease 12 (USP12), and Hypoxia." (PMID 39567970, 2024). "Knockdown of USP12 causes DNA replication stress and retards tumor growth in vivo and in vitro." (PMID 37752518, 2023). "Hence, USP12 is associated with tumor invasion and metastasis and has the potential to be a therapeutic target against tumor metastasis." (PMID 37752518, 2023). "USP12 deficiency promoted the expression of inducible nitric oxide synthase (iNOS) in MDSCs by inhibiting the p65-NF-κB signaling pathway, and MDSCs with high iNOS expression inhibit T-cell function, resulting in poorer tumor response to chemotherapy." (PMID 37752518, 2023). "Of note, the altered production of the chemokines caused by USP12 downregulation in tumour cells may also regulate T cell infiltration and function." (PMID 34381028, 2021). "To test whether USP12 downregulation is strictly associated with KRAS mutation in NSCLC, we analysed USP12 transcript levels in human LUAD tumours carrying different types of oncogenic mutations (TCGA-LUAD database)." (PMID 34381028, 2021). "Importantly, ectopic PPM1B expression inhibited tumour growth under steady-state conditions or in the accelerated course caused by USP12 knockdown." (PMID 34381028, 2021). "Therefore, USP12 downregulation in tumour cells may serve as a mechanism underlying AKT-mTOR pathway-related resistance to immunotherapy." (PMID 34381028, 2021). "USP12 can regulate p65 deubiquitination in the NF-κB signaling pathway in MDSCs, thereby mediating PD-L1 and iNOS expression and the anti-tumor immune response of CD4+ T cells." (PMID 39759114, 2025). "As a result, genes encoding ubiquitin conjugating enzymes or ligases, such as UBE2T, UBE2C, and CBLC, were up‐regulated in tumor tissues, while genes encoding deubiquitinating enzymes like OTUD1 and USP12 were down‐regulated." (PMID 37983609, 2024). "In this review, we focus on the specific role of USP12 in tumor progression and immune response to obtain new insight into the mechanisms of USP12." (PMID 37752518, 2023). "The FACS analysis of immune cell profiles showed that the expression of USP12 was negatively correlated with tumor-associated macrophages (TAMs) and PD-L1 (CD274), which were significant for tumor immune therapies." (PMID 37752518, 2023). "USP12 can act as a tumor promotor or suppressor, which depends on the specificity of cells or substrates." (PMID 37752518, 2023). "On the other hand, the identified genes with notable decreased mRNA levels playing roles in tumor growth promotion were USP12, CAT and PTK2 (FAK)." (PMID 36077645, 2022). "Among the chemokines regulated by USP12 in tumour cells, CXCL1 and CXCL8 share the chemokine receptor CXCR2 and are strong chemoattractants that recruit TAMs and MDSCs38–40." (PMID 34381028, 2021). "Taken together, these results indicate that USP12 expression in tumour cells plays an important role in reprogramming the TME." (PMID 34381028, 2021).